SNAI2 (snail family transcriptional repressor 2)
Description:
Transcriptional repressor that modulates both activator-dependent and basal transcription. Involved in the generation and migration of neural crest cells. Plays a role in mediating RAF1-induced transcriptional repression of the TJ protein, occludin (OCLN) and subsequent oncogenic transformation of epithelial cells (By similarity). Represses BRCA2 expression by binding to its E2-box-containing silencer and recruiting CTBP1 and HDAC1 in breast cells. In epidermal keratinocytes, binds to the E-box in ITGA3 promoter and represses its transcription. Involved in the regulation of ITGB1 and ITGB4 expression and cell adhesion and proliferation in epidermal keratinocytes. Binds to E-box2 domain of BSG and activates its expression during TGFB1-induced epithelial-mesenchymal transition (EMT) in hepatocytes. Represses E-Cadherin/CDH1 transcription via E-box elements. Involved in osteoblast maturation. Binds to RUNX2 and SOC9 promoters and may act as a positive and negative transcription regulator, respectively, in osteoblasts. Binds to CXCL12 promoter via E-box regions in mesenchymal stem cells and osteoblasts. Plays an essential role in TWIST1-induced EMT and its ability to promote invasion and metastasis.
Synonyms: SLUG; SLUGH; SLUGH1; SNAIL2; WS2D
Tractability: PROTAC: UniProt records ubiquitination sites on it; ubiquitination databases record sites on it.
Gene: Protein-coding gene on chromosome 8 (48,917,598 to 48,921,740, reverse strand). Ensembl gene ENSG00000019549.
Subcellular location: Nucleus; Cytoplasm
Subcellular location (Human Protein Atlas): Nucleoplasm; Cytosol
Pathways (Reactome):
Cell-Cell communication: Negative Regulation of CDH1 Gene Transcription
Developmental Biology: Transcriptional and post-translational regulation of MITF-M expression and activity
Signal Transduction: Regulation of PTEN gene transcription
Gene Ontology:
Molecular function: DNA-binding transcription repressor activity, RNA polymerase II-specific; E-box binding; protein binding; RNA polymerase II transcription regulatory region sequence-specific DNA binding; sequence-specific DNA binding; sequence-specific double-stranded DNA binding; DNA-binding transcription factor activity, RNA polymerase II-specific; RNA polymerase II cis-regulatory region sequence-specific DNA binding; chromatin binding
Biological process: cellular response to epidermal growth factor stimulus; desmosome disassembly; epithelial to mesenchymal transition; negative regulation of anoikis; negative regulation of canonical Wnt signaling pathway; negative regulation of cell adhesion mediated by integrin; negative regulation of chondrocyte differentiation; negative regulation of intrinsic apoptotic signaling pathway in response to DNA damage; negative regulation of keratinocyte proliferation; negative regulation of transcription by RNA polymerase II; negative regulation of vitamin D biosynthetic process; negative regulation of vitamin D receptor signaling pathway; neural crest cell development; Notch signaling pathway; osteoblast differentiation; pigmentation; positive regulation of cell migration; regulation of bicellular tight junction assembly; regulation of chemokine production; regulation of osteoblast differentiation; sensory perception of sound; aortic valve morphogenesis; cell migration involved in endocardial cushion formation; epithelial to mesenchymal transition involved in endocardial cushion formation; and 4 more
Cellular component: chromatin; cytosol; nucleoplasm; nucleus; cytoplasm
Genetic constraint (gnomAD): Loss-of-function variants: 2 observed, 22.22 expected, observed/expected ratio (o/e) 0.09, 90% interval 0.036 to 0.28. The upper end of that interval is the gene's LOEUF score, 0.28, which puts it in group 1 of 6, group 1 being the genes least tolerant of losing a copy. Missense variants: 235 observed, 334.45 expected, observed/expected ratio (o/e) 0.7, 90% interval 0.63 to 0.78. Synonymous variants: 134 observed, 130.2 expected, observed/expected ratio (o/e) 1.03, 90% interval 0.89 to 1.19.
Gene-disease validity (ClinGen):
ClinGen rates the evidence that SNAI2 causes each of these diseases.
Waardenburg syndrome (autosomal recessive): Limited. A disorder characterized by varying degrees of deafness and minor defects in structures arising from neural crest, including pigmentation anomalies of eyes, hair, and skin.
Homologues: Orthologues: chimpanzee SNAI2 (100% identical), macaque SNAI2 (100% identical), dog SNAI2 (98% identical), mouse Snai2 (96% identical), pig SNAI2 (95% identical), tropical clawed frog snai2 (89% identical), Drosophila melanogaster wor (49% identical). Paralogues in human: SNAI1 (54% identical), SNAI3 (51% identical), SCRT2 (40% identical), SCRT1 (40% identical), ZNF143 (25% identical), ZNF410 (25% identical), HIC1 (24% identical), PRDM1 (24% identical), ZBTB16 (24% identical), HIC2 (23% identical), ZNF76 (23% identical), PRDM10 (23% identical), and 24 more.
Diseases named in the same sentence as SNAI2 in open-access papers:
SNAI2 is named in the same sentence as 195 diseases in open-access papers, as found by Europe PMC text mining. Sharing a sentence is not in itself a finding about the gene and the disease. The quoted sentences say what the papers report.
breast cancer (267 papers, 2007 to 2025). A primary or metastatic malignant neoplasm involving the breast. "In tumors, the expression of SNAI1 and SNAI2 leads to decreased E-cadherin levels and enhanced tumor cell metastasis, and it is associated with the poor prognosis of breast cancer patients." (PMID 40830747, 2025). "SNAI2 upregulation has been associated with altered expression EMT in breast cancer cell models and has been shown to contribute to enhanced incidence of metastasis and lower survival rates in aggressive cancer phenotypes." (PMID 36980876, 2023). "Snai2 is also associated with a poor prognosis of luminal B HER2+/ERBB2+ breast cancers and directly contributes to cisplatin resistance in ovarian cancer." (PMID 35631574, 2022). "ΔNp63 has also been linked to selective regulation of EMT factors in breast cancer cells, as upregulation of SNAI2 lead to increased migration while miR-205 mediated inhibition of ZEB1 and ZEB2 resulted in EMT suppression." (PMID 34964086, 2021). "SM83 reduced the expression of Snai2, an epithelial-to-mesenchymal transition factor often associated with increased stem-like properties and metastatic potential especially in breast cancer cells." (PMID 29674627, 2018). "The pathway linking VEGFA to Sox2 upregulation, miR-452 loss and SNAI2 induction is supported by our analysis of two major data sets including over 2500 primary human breast cancers." (PMID 28504716, 2017). "A recent study showed that POU2F1 regulates expression of the EMT genes Twist1, Snai1 and Snai2 under hypoxia-dependent loss of PER2 in breast cancer." (PMID 28489585, 2017). "In breast cancer cell lines, SNAI2 levels were shown to correlate with loss of E-cadherin transport." (PMID 23717581, 2013). "This overexpression of SNAI2 is associated with the increased invasiveness of malignant breast cancers, suggesting that in cases of aggressive and invasive cancers, miR-203 may be epigenetically downregulated or silenced." (PMID 36980876, 2023). "In addition, SNAI2 upregulation is associated with an aggressive phenotype in fulvestrant-resistant breast cancer cells." (PMID 37251370, 2023). "ThPOK-kd led to an increase in the expression of EMT factors (VIM, SNAI2, ZEB1, ZEB2), basal markers and WNT/β-catenin target genes implicated in breast cancer cell proliferation." (PMID 41231242, 2025). "Repression of SNAI2 transcription by BRCA1 is a critical point in the regulation of EMT in breast cancer cells." (PMID 41345200, 2025). "In particular, the expression of TWIST1 in MCF7 breast cancer cells induced Vim and Snai2 expression but repressed CDH1 and ESR1 expression." (PMID 38893094, 2024). "SNAI2 mutant mice exhibited a decline in mammary stem cell activity and a reduced capacity to develop breast cancers." (PMID 39327614, 2024). "Snai2 overexpression has been documented in numerous cancers, including lung cancer, breast cancer, colorectal cancer, and others." (PMID 39062049, 2024). "A similar study suggested that ASB13 inhibits breast cancer metastasis by promoting SNAI2 degradation." (PMID 37251370, 2023). "This notion came from a study on mammary gland and breast cancer cells, in which Snai2 and Sox9 interplay was found to determine a mammary stem cell fate." (PMID 36669020, 2022). "Higher protein level of USP20 and SNAI2 was also demonstrated to predict worse prognosis in ER– breast cancer patients." (PMID 35508480, 2022). "The results indicated that SNAI1 and SNAI2 are highly expressed in breast cancer and are positively correlated with poor prognosis." (PMID 35898399, 2022). "The evolving role of SNAI2 as a modulator of resistance in breast cancer has motivated attention to therapeutic strategies based on reversing EMT to prevent tumor progression and re-sensitizing tumor cells to endocrine therapy." (PMID 36553576, 2022).
breast cancer (continued). "Previous studies have shown that estrogen receptor α (ERα) repressed the expression of SNAI2, and the protein level of ERα correlated inversely with SNAI2 in breast cancer cell lines and tissues." (PMID 35508480, 2022). "We were also able to observe induction of SNAI2 in BRCA1-mutated ovarian and breast cancer cell lines COV362 and MDAMB436." (PMID 35864202, 2022). "Meanwhile, they detected USP20 and SNAI2 in ER– clinical breast cancer samples, and demonstrated that USP20 positively correlated with SNAI2." (PMID 35508480, 2022). "Gene expression analyses in breast cancer have reported increased SNAI2 expression in high grade tumors, while SNAI1 showed a reduced expression, similar to our observations in MCF7 cells cultured in PDSs." (PMID 35565301, 2022). "Snai2 plays a role in breast carcinoma as well as leukemia by downregulation of E-cadherin, which supports the mesenchymal phenotype and enables metastasis of tumor cells." (PMID 35631574, 2022). "To this end, we report that PEAK1 expression in breast cancer stroma is associated with relapse in HER2-positive breast cancer and that PEAK1 is predominantly expressed in tumor associated SNAI2-positive fibroblast-like cells." (PMID 34239043, 2021). "Like PEAK1, elevated SNAI2 expression in HER2-positive breast cancer predicts reduced RFS as well as DMFS in HER2-positive breast cancer – patterns also observed for fibronectin in this same cancer subset." (PMID 34239043, 2021). "SNAI2 is a direct target of the glucocorticoid receptor GR that regulates cell migration in breast cancer, while PTPN6 is involved in glucose homeostasis via negative regulation of insulin signalling." (PMID 33513136, 2021). "Here, we determined that stromal PEAK1 expression predicts poor outcomes in HER2-positive breast cancers high in SNAI2 expression and enriched for MSC content." (PMID 34239043, 2021). "In this regard, we demonstrate that high PEAK1 expression in HER2-positive breast cancer patient tissues predicts increased disease relapse in HER2-positive breast cancers high in SNAI2 expression and mesenchymal stem cell (MSC) content." (PMID 34239043, 2021). "USP20 positively correlates with SNAI2 in breast cancer patients and a high level of USP20 is suggestive of adverse outcomes in ER- breast cancers." (PMID 34575114, 2021). "SNAI2 plays an important role in EMT and cell adhesion in breast cancer, and its upregulation is associated with breast cancer aggressiveness." (PMID 34641959, 2021). "Specifically, we identified that the fibroblastic stroma in HER2-positive breast cancer patient tissue stains positive for both nuclear SNAI2 and cytoplasmic PEAK1." (PMID 34239043, 2021). "Genes related to proliferation (MKI67, CCNA2), differentiation (EPCAM, CDH1), epithelial to mesenchymal transition (VIM, SNAI2), pluripotency and breast cancer stem cells (SOX2, NANOG, CD44) were included." (PMID 34090457, 2021). "The level of SNAI2 correlates with poor prognosis in ovarian and breast tumors, and this is similar to SNAI2 expression in breast cancer that is partially differentiated." (PMID 32154177, 2020). "miR-124 targets Slug(SNAI2, transcriptional repressor of E-cadherin)and regulates epithelial-mesenchymal transition andmetastasis of breast cancer cells." (PMID 31606975, 2020). "A previous study showed that TIMP4 secretion was regulated by the expression of LOX/SNAI2 axis and contributed to the malignant phenotype of cancers, e.g., thyroid cancer, colon cancer, and breast cancer." (PMID 31795200, 2019). "Smad4 is a predictive biomarker of poor prognosis in multiple cancers and the METABRIC data confirm that alterations in the SMAD4 and SNAI2 genes or their altered expression correlate with lower overall survival in breast cancer." (PMID 31481735, 2019). "TBX3 and SNAI2 mRNA levels were significantly lower in high‐grade breast cancers than in low‐ and intermediate‐grade breast cancers (p < 0.001), consistent with our immunohistochemical data." (PMID 30697731, 2019).
breast cancer (continued). "Earlier studies reported that SNAI1 and SNAI2 displayed a reciprocal expression in oral, breast cancer cells or during reprogramming of induced pluripotent stem cells." (PMID 31165775, 2019). "To corroborate that SNAI2 mediates the role of miR-1271 in breast cancer progression, we transfected HA-SNAI2 plasmid into miR-1271-overexpressed MDA-MB-231 cells." (PMID 30823890, 2019). "Recent data have suggested that SNAI1 and SNAI2 are differentially expressed in normal mammary glands and in mammary tumours that distinctly induces EMT program." (PMID 31165775, 2019). "Recent findings uncovered novel mechanisms through which TGF-β induces SNAI2 levels to promote EMT in breast cancer cells." (PMID 31137748, 2019). "Elevated levels of Serpine1, IL-6, and SNAI2 correlate with the pro-metastatic phenotype of breast cancer cells induced by obASCs in vitro and the increase in metastatic lesions in the lungs of mice with TNBC tumors grown with obASCs." (PMID 31118047, 2019). "By testing several breast cancer cell lines, we demonstrated that Snai2 downregulation prevents cell motility and that its expression is promoted by cIAP1." (PMID 29674627, 2018). "In summary, our data support SNAI2 as a key regulator of the aggressive phenotype observed in endocrine-resistant breast cancer cells and a prognostic biomarker in ER+ advanced breast cancer treated with endocrine therapy." (PMID 29921289, 2018). "The reduction of Snai2 mediated by cIAP1 silencing was further confirmed by using two different siRNAs and employing a number of breast cancer cell lines expressing detectable levels of Snai2." (PMID 29674627, 2018). "Previous studies have demonstrated that SNAI2 increases stemness in breast cancer cells when co-expressed with SOX9 or through regulation of stem cell markers, including c-Myc, SOX2 and Oct4, possibly contributing to drug resistance." (PMID 29921289, 2018). "Inhibition of SNAI2 induced epithelial characteristics, reduced cell motility, and impaired growth of fulvestrant-resistant breast cancer cells." (PMID 29921289, 2018). "Correlation between high SNAI2 expression in primary breast tumors and shorter relapse-free survival has been previously demonstrated in ER+ breast cancer." (PMID 29921289, 2018). "Nevertheless, our study is the first to our knowledge to report the prognostic value of SNAI2 in patients with ER+ advanced breast cancer treated with endocrine therapy." (PMID 29921289, 2018). "Mean transcript levels of SNAI2 were higher in the basal B breast cancer cells with low FRK transcript levels as compared to the Luminal cells (P<0.05)." (PMID 29348886, 2017). "MYC is a target of WNT/β-catenin signaling, which induces epigenetic repression of BRCA1 expression by means of snail family zinc finger 2 (SNAI2) and is associated with basal-like breast cancer and EMT, including metastasis." (PMID 27590516, 2016). "The result showed that siRNA transfection of breast cancer cell lines led to over 80% reduction in SNAI2 expression as measured by qRT-PCR." (PMID 27528030, 2016). "The restoration of miR-203 in breast cancer cells inhibits tumor cell invasion in vitro and lung metastatic colonization in vivo by repressing SNAI2, suggesting that the SNAI2 and miR-203 regulatory loop has an important role in EMT and tumor metastasis." (PMID 29263891, 2016). "The ability of BRCA1 to mediate mammary tumor differentiation has been attributed to its inhibition of Slug (Snai2) and Twist expression, key mediators of EMT." (PMID 25970777, 2015). "Previous studies demonstrated that Snai2 is a transcriptional repressor of CLDN1 in epithelial breast cancer cells." (PMID 26067567, 2015). "Consistent with the association between TRPM7 and SNAI2 expression levels in our neuroblastoma cell models, we previously showed that TRPM7 activity induces cytoskeletal relaxation in breast cancer cells as well as in neuroblastoma cells." (PMID 25797249, 2015).